MYBBP1A (MYB binding protein 1a)
Diseases named in the same sentence as MYBBP1A in open-access papers (continued):
Sharing a sentence is not in itself a finding about the gene and the disease.
tumor (17 papers, 2012 to 2025). "Currently, although MYBBP1A overexpression has been associated with poor prognosis in hepatocellular carcinoma, it has been found to act as a tumor suppressor gene in several contexts." (PMID 31968688, 2020). "In this context, 85% of ccRCC occurs when the loss of MYBBP1A causes an increase in the population of tumor stem cells and the metabolic reprogramming of glycolysis to OXPHOS." (PMID 31968688, 2020). "All these data strongly suggest that the MYBBP1A gene is a tumor suppressor and that a loss of this gene favors metastatic phenotypes." (PMID 30781655, 2019). "Although the underlying molecular mechanism, how MYBBP1A regulates the tumor cell physiology remains to be elucidated our data suggest that tumor cells with reduced MYBBP1A protein expression belong to a subpopulation of slow-cycling cells with high mobility." (PMID 22339894, 2012). "Therefore, the combination of these two effects caused by the decreased expression of MYBBP1A provides a selective advantage to tumor cells." (PMID 31968688, 2020). "This association of the loss of MYBBP1A with the appearance of metastasis and worse prognosis supports the idea that a reduction in MYBBP1A expression leads to an increase in the population of tumor stem cells." (PMID 31968688, 2020). "Hence, MYBBP1A loss will occur in a tumor with expression of c-MYB and will have functionality by increasing c-MYB activity." (PMID 30781655, 2019). "In c-MYB + lines, the reduction in MYBBP1A levels causes an increase in the number of Cancer Stem Cells (CSCs) the capacity of tumor-formation and the expression of genes related to the regulation of the pluripotency of tumor stem cells and the epithelium–mesenchyme transition." (PMID 31968688, 2020). "Furthermore, the loss of MYBBP1A occurs in 8%–9% of renal tumors and may occur in a percentage of other tumors, according to its role as a potent tumor suppressor." (PMID 31968688, 2020). "Interestingly, the analysis of MYBBP1A low tumor samples by different subtypes of RCC points to MYBBP1A loss is more frequent in chRCCs, which could be a suitable subgroup to target oxidative pathways as an alternative therapeutic approach." (PMID 31066170, 2019). "Our results confirmed the roles of β‐catenin, SMAD2, and SMAD3 in promoting EMT, and identified the roles of tumor suppressor MYBBP1A, NKRF, and MYPOP in repressing the EMT process." (PMID 37566765, 2023). "When studying the effect of reducing the expression of MYBBP1A in vivo in xenograft models, we observed an increase in tumor size and the appearance of metastases only when injecting cells expressing c-MYB." (PMID 31968688, 2020). "As the deacetylase activity of SIRT7 on H3K18Ac is necessary for the maintenance of the fundamental properties of tumor cells, the inhibition of SIRT7 by MYBBP1A suggests that MYBBP1A functions as a tumor suppressor." (PMID 31968688, 2020). "In all these processes, MYBBP1A acts as a tumor suppressor, regulating the evolution and malignity of cells." (PMID 31968688, 2020). "On the other hand, the reduction in MYBBP1A levels increases tumor properties only in cell lines that express c MYB." (PMID 31968688, 2020). "In summary, our data support the role of MYBBP1A as a tumor suppressor by regulating c‐MYB and PGC1α." (PMID 31066170, 2019). "To examine the role of MYBBP1A in human tumor progression, in relation to an increase in c‐MYB and PGC1α, we used public transcriptome databases." (PMID 31066170, 2019). "To this end, we first checked MYBBP1A expression in several arrays of paired normal/tumor tissue samples from the same patients." (PMID 31066170, 2019).
tumor (continued). "Our data support the role of MYBBP1A as a tumor suppressor by repressing c-MYB, acting as an important regulator of the plasticity of tumor cells." (PMID 30781655, 2019). "Our data clearly showed that MYBBP1A knock down increased the stem cell-like phenotype in some tumor cells and that these tumor cells seemed to have significant levels of c-MYB." (PMID 30781655, 2019). "We have identified a group of tumor samples that shows low expression of MYBBP1A and high expression of PGC1α and c‐MYB target genes involved in metabolic pathways." (PMID 31066170, 2019). "Our data strongly support the role of MYBBP1A as a tumor suppressor via regulation of c‐MYB and PGC1α." (PMID 31066170, 2019). "We found that loss of MYBBP1A release PGC1α activity and transcription activation through c‐MYB switching tumor bioenergetics, increasing glutaminolysis and sensitivity to oxidative channel inhibition." (PMID 31066170, 2019). "In fact, tumor cells with low MYBBP1A are more sensitive to mitochondrial respiratory channel inhibition by rotenone, suggesting some degree of dependency of these cells from the oxidative metabolism." (PMID 31066170, 2019). "In this study, we characterized the role of MYBBP1A by experiments in cell lines, xenografts and human tumor samples." (PMID 30781655, 2019). "Even then, this association supports the fact that the CSC phenotype is the result of MYBBP1A loss, as it has been reported that CSC are involved in metastasis and tumor recurrence." (PMID 30781655, 2019). "This PGC1α activation suggests the reorientation of tumor cell metabolism toward OXPHOS in MYBBP1A‐downregulated and c‐MYB‐positive cells." (PMID 31066170, 2019). "Our data support the role of MYBBP1A as a tumor suppressor by regulating stemness via repression of c-MYB." (PMID 30781655, 2019). "We believe that the combined effects elicited by MYBBP1A downregulation confer selective advantages over other tumor cells." (PMID 31066170, 2019). "We conclude that MYBBP1A is an essential gene with novel roles at the pre-mitotic level and potential tumor suppressor activity." (PMID 23056166, 2012). "To further support the opposing role of MYBBP1A in tumor cell physiology, we analyzed its transcript and protein levels in well-established human HNSCC cell lines (Fadu, Cal-27, SCC-4, SCC-9, and SCC-25)." (PMID 22339894, 2012). "A strong nuclear staining for Mybbp1a protein was detected in most tumor cells (84%) of primary tumors, which was significantly reduced on tissue sections from local recurrences (35%)." (PMID 22339894, 2012). "To confirm altered Mybbp1a protein expression we performed immunohistochemical staining on tissue sections derived from the orthotopic mouse tumor model." (PMID 22339894, 2012). "We confirmed significantly reduced MYBBP1A protein levels on tissue sections of recurrent mouse tumors compared to primary tumors by immunohistochemistry, and found aberrant MYBBP1A protein levels also in tumor samples of HNSCC patients." (PMID 22339894, 2012). "This switch may confer advantages over other tumor cells, indicating the biological relevance of the MYBBP1A downregulation in cancer." (PMID 31968688, 2020). "Therefore, MYBBP1A acts as a tumor suppressor in multiple aspects related to cell physiology, most of them very relevant for tumorigenesis." (PMID 31968688, 2020). "For this reason, it has been proposed that tumor cells with reduced levels of MYBBP1A could represent a subpopulation of slow-growing but highly migratory cells involved in relapse and metastasis." (PMID 31968688, 2020).
tumor (continued). "Likewise, these target genes are mainly related to the metabolic pathways, confirming the role of MYBBP1A in the regulation of the tumor cell metabolism through c-MYB and PGC-1α." (PMID 31968688, 2020). "A significant reduction in Mybbp1a levels has been observed in recurrent tumors of mice in comparison to the levels in primary tumors, with the same result observed in 50% of analyzed human tumor samples." (PMID 31968688, 2020). "Finally, because we observed a shift from glycolysis to OXPHOS when we reduced MYBBP1A mRNA levels in our cellular model, we used these public databases to confirm that this metabolic shift is also observed in tumor samples." (PMID 31066170, 2019). "Our work supports the theory that MYBBP1A acts as a tumor suppressor that interacts with c-MYB." (PMID 30781655, 2019). "In this work, we characterized the role of MYBBP1A as a new tumor suppressor." (PMID 30781655, 2019). "However, if the downregulation of MYBBP1A is an important trait required for the evolution of these cells, it must be maintained throughout tumor growth; therefore, we should be able to identify it in human tumors." (PMID 31066170, 2019). "A previous loss of function screen to identify genes that might play a role in tumorigenesis identified MYB binding protein 1A (MYBBP1A) gene as a potential new tumor suppressor gene." (PMID 30781655, 2019). "However, there is not completely understood the molecular mechanism through which MYBBP1A would regulate the tumor metabolism." (PMID 31066170, 2019). "The MYBBP1A gene encodes the MYB binding protein 1a, involved in many essential cellular processes, including cell cycle control, mitosis, the nuclear stress response, and tumor suppression." (PMID 30832275, 2019). "In addition, MYBBP1A is regulated by the VHL tumor suppressor, which regulates MYBBP1A degradation in an iron‐ and proteasome‐dependent manner." (PMID 31066170, 2019). "Interestingly, the effect of MYBBP1A as a tumor suppressor is only observed in the presence of c-MYB." (PMID 30781655, 2019). "However, Ras-transformed, Mybbp1a-down-regulated NIH-3T3 cells showed significantly accelerated tumor formation in nude mice compared to control Ras-transformed cells." (PMID 23056166, 2012). "In contrast, high MYBBP1A protein levels were negatively correlated with the migration capacity, further supporting a regulatory function of MYBBP1A as a promoter of tumor cell proliferation and inhibitor of migration." (PMID 22339894, 2012). "The results therefore indicate that Mybbp1a has a tumor-suppressive function." (PMID 23056166, 2012). "The NIH3T3 transformation data also suggest that Mybbp1a might be able to act as a tumor suppressor gene in some contexts." (PMID 23056166, 2012). "In the early phase of HNSCC development MYBBP1A promotes tumor cell proliferation, while in advanced tumors inactivation of MYBBP1A induces accelerated tumor cell migration and invasion, and thereby hampers the loco-regional control by facilitating lymph node metastasis and tumor recurrence." (PMID 22339894, 2012). "In line with this assumption, staining of tissue sections derived from the mouse model revealed 44% Ki67-positive in the primary tumor, while recurrent tumors with decreased immunoreactivity for Mybbp1a showed a prominent reduction of Ki67 staining (14% of the total cells)." (PMID 22339894, 2012). "Besides its role as a nucleolar transcriptional regulator, MYBBP1A is essential in mice prior to blastocyst formation, is involved at premitotic level, and may display tumor suppressor activity." (PMID 31066170, 2019).
tumor (continued). "MYBBP1A downregulation in HSNCC cell lines increases migration but decreases cell growth, generating a sub-population of slow-cycling mobile cells that may be implicated in local tumor recurrence and metastasis." (PMID 30781655, 2019). "SCC-7 cells with reduced Mybbp1a levels exhibited impaired proliferation compared to control transfected cells, 12% and 24% cell in S-phase, respectively, suggesting a positive correlation between Mybbp1a protein levels and tumor cell proliferation in primary tumors." (PMID 22339894, 2012). "Moreover, Mybbp1a may act as a tumor suppressor, as its down-regulation facilitates the transformation of NIH3T3 cells by the HRas oncogene." (PMID 23056166, 2012). "In renal cancer, decreased levels of MYBBP1A have been observed to increase c-MYB activity and, in response, induce the dedifferentiation of mature tumor cells into tumor stem cells." (PMID 40813991, 2025). "We especially reviewed the relationships between MYBBP1A, the inhibitory role it plays by binding and inactivating c-MYB and its regulation of PGC-1α, leading to an increase in the stemness and the tumor stem cell population." (PMID 31968688, 2020). "Taken together, the reduction in the expression of MYBBP1A induces the activation of c-MYB, which ultimately results in an increase in the tumor stem cell phenotype." (PMID 31968688, 2020). "To confirm this point we have analyzed the expression of c-MYB in all tumor samples from our cohort and correlated to VHL and MYBBP1A expression." (PMID 30781655, 2019). "24-mCAF up-regulates Myb binding protein 1A (MYBBP1A), a tumor suppressor." (PMID 34072678, 2021). "Tumor cells expressing the control vector do not grow in medium containing only glutamine; however, cells with low levels of MYBBP1A grow fast, indicating a switch to OXPHOS metabolism." (PMID 31066170, 2019). "It has already been reported that in some contexts, MYBBP1A acts as a tumor suppressor, but no clear mechanism has been given." (PMID 30781655, 2019). "In addition, MYBBP1A could be involved in the plasticity of bioenergetics in cancer cells, as MYBBP1A has been proposed to be regulated by the von Hippel-Lindau (VHL) tumor suppressor." (PMID 30781655, 2019). "The existence of a slow-cycling subpopulation of MYBBP1A negative tumor cells in HNSCC patients could be of high clinical importance since most current therapeutic regimens target the rapidly proliferating tumor bulk." (PMID 22339894, 2012). "Mybbp1a down-regulated NIH-3T3 cells did not induce tumor formation on their own." (PMID 23056166, 2012). "Concerning the later phenotype, improved migration and invasion capacity of tumor cells with low or absent MYBBP1A expression might be, at least in part, due to a reduction in membrane proteins that are critically implicated in cell-cell adhesion, such as E-Cadherin." (PMID 22339894, 2012).
cancer (10 papers, 2012 to 2023). A tumor composed of atypical neoplastic, often pleomorphic cells that invade other tissues. "Originally, MYBBP1A was reported as mapping to 17p13.3, where the loss of heterozygosity is observed with high frequency (50%–80%) in different types of cancer, including sporadic breast and ovarian cancer, medulloblastomas, astrocytomas, osteosarcomas, leukemias, bladder cancer and lung cancer." (PMID 31968688, 2020). "MYBBP1A has been studied in several cancer cell lines and Drosophila, where it is reported to be localized in the nucleolus." (PMID 38064566, 2023). "We explored the different roles of MYBBP1A in different aspects of cancer, such as mitosis, cellular senescence, epigenetic regulation, cell cycle, metabolism plasticity and stemness." (PMID 31968688, 2020). "In human HeLa cancer cells, MYBBP1A was efficiently down-regulated by three tested siRNAs, in particular siRNA-1 and -3; these achieved about 80% down-regulation within 48 h of transfection." (PMID 23056166, 2012). "Down-regulation of MYBBP1A in normal primary cells like ES and MEFs has an effect superimposable to that on human cancer HeLa cells, i.e. a strong decrease in growth rate and increased apoptosis." (PMID 23056166, 2012). "pVHL is known to regulate ECM deposition and defect in the hypoxia-depend regulation of MYBBP1A may have a role in cancer progression." (PMID 32603638, 2020). "Therefore, our results provide a novel insight into the function of the nucleolar protein MYBBP1A in the biology of cancer cells." (PMID 23388179, 2013). "However, more detailed studies are required to highlight the molecular function of MYBBP1A under physiological and pathological conditions, including cancer." (PMID 22339894, 2012). "It will be a major challenge for the future to proof the concept whether the reactivation of MYBBP1A expression could serve as a novel option for anti-cancer therapy for patients with advanced HNSCC and thereby ameliorate the therapy response rate." (PMID 22339894, 2012). "Therefore, MYBBP1A could also be involved in the metabolic plasticity of cancer cells." (PMID 31066170, 2019). "We have examined the function of MYBBP1A in vivo, in primary mouse cells (ES and MEFs), in immortalized NIH3T3 and in cancer HeLa cells." (PMID 23056166, 2012). "The role of MYBBP1A in cancer insurgence is not completely clear; however, recent studies linked this nuclear protein to the regulation of anoikis, a particular programmed cell death that occurs when specific cell detach from the surrounding extracellular matrix (ECM)." (PMID 32603638, 2020). "However, the function of MYBBP1A in cancer prevention has not been elucidated." (PMID 23388179, 2013). "Interestingly, cancer cells that express c-MYB and do not express pVHL are the ones that can take advantage of the MYBBP1A knock down." (PMID 30781655, 2019). "Interestingly, cancer cells that express c‐MYB and do not express pVHL are the ones that can take advantage of MYBBP1A downregulation." (PMID 31066170, 2019).
infection (2 papers, 2012 to 2018). The state of being infected such as from the introduction of a foreign agent such as serum, vaccine, antigenic substance or organism. "The analysis of a representative cell showed that Mybbp1A remained associated with nucleoli upon infection for prolonged times (∼20 h under the MOI used), followed by a short period during which Mybbp1A separated from nucleoli and formed heterogeneous structures inside the nucleoplasm." (PMID 29997215, 2018). "Mybbp1A remained in nucleoli until late phases of infection, when it relocalized to replicated viral dsDNA to form ViPR bodies in the nucleoplasm." (PMID 29997215, 2018).
MYBBP1A also shares sentences with these, for which no sentence is quoted: cardiac ischemia (1 paper); choroid plexus papilloma (1); liver cancer (1); non-small cell lung carcinoma (1); osteopetrosis (1); Parkinson disease (1); psoriasis (1); thrombosis (1).